TAOK1 (TAO kinase 1)
Diseases named in the same sentence as TAOK1 in open-access papers (continued):
Sharing a sentence is not in itself a finding about the gene and the disease.
Parkinson disease (1 paper, 2025). A progressive degenerative disorder of the central nervous system characterized by loss of dopamine producing neurons in the substantia nigra and the presence of Lewy bodies in the substantia nigra and locus coeruleus. "In our series, WGS analysis enabled diagnosis of PRKN‐related Parkinson disease, TAOK1‐related neurodevelopmental disorder, and Usmani‐Riazuddin syndrome, which had significant implications for the clinical care of the patients and families concerned." (PMID 38840441, 2025). "In all three cases, WGS identified CNVs and confirmed zygosity and pathogenicity, resulting in genetic diagnoses of PRKN‐related Parkinson disease, TAOK1‐related neurodevelopmental disorder, and AP1G1‐related Usmani‐Riazuddin syndrome." (PMID 38840441, 2025).
prostatic diseases (1 paper, 2023). "Therefore, TAOK1 may play a role as one of the factors in managing prostatic diseases." (PMID 38136890, 2023).
steatosis (1 paper, 2023). Increased lipid within the cytoplasm of cells. "Consistent with the analysis of histological steatosis score, we detected a positive correlation between the hepatic TAOK1 transcript and liver fat content measured by magnetic resonance spectroscopy." (PMID 36930872, 2023). "In addition, we observed that the patient subset presenting NAS ≥5 (indicates definitive NASH; n=24) had a slight but significant increase in TAOK1 abundance compared with the patient subset presenting NAS ≤4 (indicates simple steatosis or borderline NASH; n=35)." (PMID 36930872, 2023).
cancer (12 papers, 2016 to 2025). A tumor composed of atypical neoplastic, often pleomorphic cells that invade other tissues. "In addition to cancer, TAOK1 and MAP4K5 is implicated in neurodegenerative disorders." (PMID 33167727, 2021). "This study investigates the therapeutic potential of Deferasirox (DFO), an iron chelator, in ESCC by targeting TAOK1, an STE20-type kinase implicated in cancer development." (PMID 40003990, 2025). "In summary, these findings provide a strong rationale for repurposing DFO in the treatment of ESCC and highlight TAOK1 as a promising target in kinase-driven cancers." (PMID 40003990, 2025). "Thousand and one amino-acid kinase 1 (TAOK1) has been identified as a potential target for drug research in various cancers." (PMID 36158126, 2022). "Additionally, corylifol A ameliorates muscle atrophy by inhibiting the TAOK1/p38-MAPK/FoxO3 pathway in cancer cachexia." (PMID 40003990, 2025). "Recent studies have shown a growing research focus on TAOK1 in cancer malignancies." (PMID 40003990, 2025). "Finally, other proteins identified in our 4 × 4 proteomic comparison of PDAC vs HC organoid EVs with more variability in the larger PDAC panel (PTPRJ, MUC16, TAOK1) are also reported markers of tumor-development in several cancer models." (PMID 35241737, 2022). "TAOK1 was found to be overexpressed in lung cancer tissues compared to normal lung tissues in a study using in situ hybridization to search for alterations of serine/threonine kinase expression in cancers." (PMID 33050415, 2020). "Other KDs were associated with signal transduction and kinase activity (PRKCA, TAOK1, and ADRBK1), membrane transport (SLC9A3R1), metabolism (PPP1R3B), gene regulation (USF1), and immune responses and cancer (SLAMF8, SRC, and KIAA0100)." (PMID 41402937, 2025). "Consistently, the mRNA expression of Slug and Zeb1, 2 transcription factors critical for epithelial-mesenchymal transition of cancer cells, was decreased in HepG2-NTCP cells where TAOK1 was knocked down." (PMID 36930872, 2023). "As an example, TAOK1, an understudied kinase, shows high co-expression with PIK3C2A in 17,382 normal samples and 1376 cancer samples in the Genotype-Tissue Expression project (GTEx, version 8) and the Cancer Dependency Portal (DepMap, 20Q4), respectively." (PMID 34537014, 2021). "An examination of publicly available (TCGA) human RNA-seq data, CNA, and methylation revealed that NF2 and TAOK1 are deleted and under-expressed, the GDI2 promoter is hypermethylated, and APC is lost in a subset of human cancers." (PMID 33808166, 2021). "The results showed that the expression of TAOK1, CMTM6 and CNOT7 were significantly lower in the adjacent cancers, while the expression of WASF3 was significantly higher in the adjacent cancers." (PMID 34336682, 2021). "The function and involvement of TAOK1-CRYBA1 in cancer has not been reported, and its functional significance should be determined." (PMID 32825119, 2020). "TAOK1 belongs to the mammalian STE20 kinase family, and its alteration, in turn, leads to changes in the biological behavior of cells, allowing uncontrolled cancer cell growth, aberrant proliferation, transformation and motility, and ultimately invasion and metastasis." (PMID 36158126, 2022).
tumor (11 papers, 2012 to 2025). "TAOK1 encodes a serine/threonine kinase that acts as a tumor suppressor via direct phosphorylation of YAP, preventing nuclear YAP translocation and instead resulting in cytoplasmic accumulation and degradation." (PMID 33808166, 2021). "Here, (R,S′)-MNF exerted a potent repression of the Hippo-YAP/TAZ signaling in PANC-1 tumor xenografts with the downregulation of genes encoding key mediators (TAOK1, MST2, MOBK1B), transcriptional regulators (WWTR1, TEAD4), and downstream pro-survival genes CYR61, BIRC2, and MCL1." (PMID 35256673, 2022). "Concomitant loss of NF1 and TAOK1 resulted in tumor formation in vivo." (PMID 33808166, 2021). "Surprisingly, TAOK1 overexpression in NSCLC promotes tumor cell growth and invasion, which is associated with downregulation of its downstream protein WWC1, and this result might provide a robust research basis to inquire about the precise therapeutic targets for NSCLC." (PMID 36158126, 2022). "IHC and quantitative analysis revealed that DFO treatment significantly decreased the expression of Ki-67, a proliferation marker, and TAOK1 in tumor tissues from both the LEG170 and HEG63 models." (PMID 40003990, 2025). "We demonstrated the tumor suppressive effects of TAOK1 and showed that the oncogenic effects of ELFN1-AS1 were achieved to some extent by TAOK1." (PMID 39528458, 2024). "For instance, fusions of oncogenic proteins TAZ, YAP1, and HIPK2 preserve their tumor-promoting function, while fusions of tumor suppressors, such as NF2, LATS1, FAT1, PTPN14, DCHS2, TAOK1, and TAOK3, results in loss of their function." (PMID 38499647, 2024). "Mechanically, ELFN1-AS1 plays an oncogenic role by binding to the protein kinase domain of thousand and one amino acid protein kinase (TAOK1), a tumor suppressor in GC, and disrupting the TAOK1-STK3 interaction, leading to decreased STK3 phosphorylation." (PMID 39528458, 2024). "The subcutaneous xenograft tumor formation assay and lung metastasis assay after cotransfecting GC cells with si-ELFN1-AS1 and si-TAOK1 showed that TAOK1 knockdown partially rescued the effect of ELFN1-AS1 slicing on tumor formation and metastasis." (PMID 39528458, 2024). "A previous study reported that Tao-1, a homolog of TAOK1, in Drosophila can phosphorylate Hpo kinase, thereby regulating the Hippo-Salvador-Warts tumor suppressor pathway." (PMID 39528458, 2024). "Top 10 candidates also included proteins associated with tumor progression (LAMA5, SDCBP, TENA, PTPRJ, MUC16, TAOK1; see “Discussion”)." (PMID 35241737, 2022). "Individual loss-of-function mutations in the TAOK1, GDI2, NF1, and APC genes resulted in transformation of immortalized human Schwann cells and tumor formation in a xenograft model." (PMID 33808166, 2021). "Furthermore, TAOK1 contributed to tumor-promoting effects, manifested by facilitating NSCLC cell proliferation, invasion, and suppressing apoptosis in vitro and accelerating xenograft formation in vivo by reducing WWC1 expression." (PMID 36158126, 2022). "Thus, the results confirmed that TAOK1 is a tumor suppressor in vitro." (PMID 39528458, 2024). "Western blotting results revealed that TAOK1 silencing decreased TAOK1 protein expression and increased WWC1 levels in tumor tissues of rats." (PMID 36158126, 2022). "In this study, we showed that DFO dramatically inhibited ESCC cells and PDX tumor growth by directly binding to and inhibiting TAOK1 kinase activity, rather than through its iron-chelating properties." (PMID 40003990, 2025). "Functional studies showed that TAOK1 regulates NSCLC cell behavior and tumor formation in vivo." (PMID 36158126, 2022).
neurodevelopmental disorder (5 papers, 2022 to 2026). A behavioral and cognitive disorder with onset during the developmental period that involves impaired or aberrant development of intellectual, motor, or social functions. "Heterozygous variants in TAOK1 have been reported in children with neurodevelopmental disorders, with or without macrocephaly, hypotonia and mild dysmorphic traits." (PMID 38443934, 2024).
neurological disorders (1 paper, 2024). "The role of Taok1 in neurological disorders is multifaceted and has been associated with WMI-related processes, such as inflammation and apoptosis." (PMID 38534387, 2024).
TAOK1 also shares sentences with these, for which no sentence is quoted: tauopathy (3 papers); autism spectrum disorder (2); breast tumors (2); non-small cell lung carcinoma (2); Action tremor (1); acute myeloid leukemia (1); anxiety disorder (1); Brain Abnormalities (1); cervical squamous cell carcinoma (1); endometriosis (1); esophageal carcinoma (1); esophageal squamous cell carcinoma (1); genetic disorders (1); glioma (1); hearing loss (1); heart failure (1); inflammatory bowel disease (1); Intellectual disability (1); intellectual impairment (1); ischemia reperfusion injury (1); lenti-virus infection (1); microcephaly (1); pancreatic cancer (1); periventricular nodular heterotopia (1); sensorineural hearing loss (1); Sepsis (1); ulcerative colitis (1).